MKRN3 (makorin ring finger protein 3)
Description:
E3 ubiquitin ligase catalyzing the covalent attachment of ubiquitin moieties onto substrate proteins. Acts as a key developmental timer that helps ensure puberty begins at the appropriate age, by inhibiting premature activation of the reproductive hormone cascade. Epigenetically regulates GNRH1 transcription by disrupting the binding of methyl-DNA binding protein 3/MBD3 to the promoter of GNRH1. Mechanistically, mediates the non-proteolytic ubiquitination of MBD3 at multiple sites with 'Lys27' ubiquitin linkages and thereby regulates the methylation status of the genome, including GNRH1 promoter. Modulates the stability and translation of GNRH1 mRNA by mediating the non-proteolytic ubiquitination of PABP family members PABPC1, PABPC3 and PABPC4 at multiple sites. Also participates in the maintenance of genomic and epigenomic stability by regulating the abundance of APEX2 via 'Lys-48'-linked ubiquitination.
Synonyms: D15S9; RNF63; ZNF127; ZFP127; MGC88288; CPPB2
Tractability: Antibody: the Human Protein Atlas places it where antibodies can reach. PROTAC: ubiquitination databases record sites on it; its protein half-life has been measured.
Target class: Enzyme; Transferase
Gene: Protein-coding gene on chromosome 15 (23,565,674 to 23,630,075, forward strand). Ensembl gene ENSG00000179455.
Subcellular location: Nucleus
Subcellular location (Human Protein Atlas): Cytosol; Plasma membrane; Nucleoplasm
Gene Ontology:
Molecular function: identical protein binding; protein binding; ubiquitin protein ligase activity; RNA binding; metal ion binding
Biological process: protein polyubiquitination; protein ubiquitination
Cellular component: nucleus; ribonucleoprotein complex
Genetic constraint (gnomAD): Loss-of-function variants: 1 observed, 2.33 expected, observed/expected ratio (o/e) 0.43, 90% interval 0.15 to 1.66. That is too few expected variants to judge how well the gene tolerates losing a copy. Missense variants: 749 observed, 697.37 expected, observed/expected ratio (o/e) 1.07, 90% interval 1.01 to 1.14. Synonymous variants: 301 observed, 263.47 expected, observed/expected ratio (o/e) 1.14, 90% interval 1.04 to 1.26.
Homologues: Orthologues: rabbit MKRN3 (76% identical), rat Mkrn3 (69% identical), mouse Mkrn3 (69% identical), dog MKRN3 (64% identical), tropical clawed frog mkrn1 (41% identical), zebrafish mkrn1 (39% identical), chimpanzee MKRN3 (33% identical), Drosophila melanogaster Mkrn1 (27% identical), Caenorhabditis elegans lep-2 (26% identical), Drosophila melanogaster CG5347 (24% identical), Drosophila melanogaster CG5334 (17% identical), Drosophila melanogaster CG12477 (17% identical). Paralogues in human: MKRN1 (49% identical), MKRN2 (28% identical).
Diseases named in the same sentence as MKRN3 in open-access papers:
MKRN3 is named in the same sentence as 34 diseases in open-access papers, as found by Europe PMC text mining. Sharing a sentence is not in itself a finding about the gene and the disease. The quoted sentences say what the papers report.
central precocious puberty (35 papers, 2015 to 2025). "This study found increased gonadotropin releasing hormone (GnRH) and decreased gonadotropin inhibiting hormone (GnIH) in the hypothalamus of the central precocious puberty (CPP) rabbit model with MKRN3 gene mutation." (PMID 39854156, 2025). "Makorin ring finger protein 3 gene (MKRN3) gene mutation is the most common genetic cause of central precocious puberty (CPP) in children." (PMID 39854156, 2025). "In fact, Bessa analyzed a small cohort of 10 Brazilian girls affected by familial forms of central precocious puberty, some of them with known mutations in the MKRN3 and DLK1 genes." (PMID 38909248, 2024). "Paternal deletion or loss-of-function mutations in MKRN3 are thought to contribute to hypogonadism, infertility, and the rare cases of central precocious puberty (CPP) in PWS patients." (PMID 37685915, 2023). "Makorin ring finger protein 3 (MKRN3) was identified as an inhibitor of puberty initiation with the report of loss-of-function mutations in association with central precocious puberty." (PMID 37092553, 2023). "Germline mutations in the makorin ring finger protein 3(MKRN3) gene cause central precocious puberty (CPP), which is epidemiologically associated with various diseases in adulthood, including cancer." (PMID 36531055, 2022). "Imprinted MKRN3 is expressed in hypothalamic regions essential for the onset of puberty and mutations in the gene have been found in patients with central precocious puberty." (PMID 36714607, 2022). "Loss-of-function mutations in Makorin Ring Finger Protein 3 (MKRN3) are the most common identified genetic cause of central precocious puberty compared to sporadic cases." (PMID 34297502, 2021). "In the present study we performed the first descrition of 3 family cases of central precocious puberty duo to novel MKRN3 gene mutation detected by NGS in the Russian Federation." (PMID 34297502, 2021). "In our study, functional tests indicated that MKRN3 (G93S) is a loss-of-function mutation, which attenuated the inhibition of GnRH1-related signaling, suggesting this mutant can lead to central precocious puberty." (PMID 34421985, 2021). "Recently, MKRN3 has emerged as a pubertal repressor, as mutations in MKRN3 were found in human patient of central precocious puberty (CPP) MKRN3 across different races." (PMID 33744966, 2021). "Here we reported that the three members of PABPs, including PABPC1, PABPC3 and PABPC4, were identified as novel substrates for MKRN3, whose deletion or loss-of-function mutations were genetically associated with human central precocious puberty (CPP)." (PMID 33744966, 2021). "In this study, a novel MKRN3 variant (c.G277A/p.Gly93Ser) was found in a Chinese patient with familial precocious puberty, and functional tests indicated it as a loss-of-function mutation." (PMID 34421985, 2021). "In particular, deleterious mutations of MKRN3 have been identified as the first genetic cause of central precocious puberty in boys and girls." (PMID 31697675, 2019). "More direct evidence was provided by the demonstration that central precocious puberty (CPP) due to loss-of-function mutations in the paternally expressed imprinted genes MKRN3 (makorin ring finger 3) and DLK1 (delta-like 1 homolog) is an imprinting disorder." (PMID 30466473, 2018). "The association of MKRN3 polymorphism and precocious puberty was studied previously and the author reported low frequency of MKRN3 mutations in central precocious puberty in Korean girls." (PMID 30053798, 2018). "In this study, the authors researched 40 members of 15 families with precocious puberty from several ethnic groups (12 Brazilian families, 2 American families, and one Belgian familys) and demonstrated the effect of mutations of MKRN3 for precocious puberty." (PMID 30053798, 2018). "The MKRN3 gene is currently the most commonly implicated in familial central precocious puberty." (PMID 38367171, 2024).
central precocious puberty (continued). "The role of makorin ring finger protein 3 (MKRN3) in the regulation of pubertal timing was revealed when loss-of-function mutations were identified in patients with central precocious puberty (CPP), which to date, represent the most commonly known genetic cause of this condition." (PMID 36187104, 2022). "In particular an increasing number of deleterious mutations has been described in both familial and apparently sporadic cases, making MKRN3 deficiency the most frequent genetic cause of central precocious puberty with a prevalence ranging from 0.5-17.5% in sporadic cases to 9-46% in familial cases." (PMID 36187104, 2022). "Pathogenic variants in MKRN3 can disrupt this regulatory function, leading to conditions such as central precocious puberty (CPP)." (PMID 38737552, 2024). "Loss-of-function mutations of MKRN3 gene cause the most cases of familial central precocious puberty (CPP)." (PMID 36619551, 2022). "The genetic alterations of MKRN3 have been confirmed as the cause of central precocious puberty (CPP), including deleterious mutations in the coding region and the promoter and 5′-UTR regulatory regions of the MKRN3 gene." (PMID 34359112, 2021). "Given the atypical presentation and the need to rule out genetic causes, a genetic panel was conducted, including sequencing of the MKRN3, DLK1, and KISS1R genes, which are associated with familial cases of central precocious puberty." (PMID 40860784, 2025). "Central precocious puberty (CPP) is driven by premature activation of the hypothalamic–pituitary-gonadal axis, often due to hypothalamic tumors, congenital abnormalities, or genetic mutations such as MKRN3 deficiency." (PMID 40860784, 2025). "Through its E3 ubiquitin ligase activity, MKRN3 serves as a negative regulator of GnRH secretion on the transcriptional and translational level, and MKRN3 depletion contributes to hypogonadism, infertility, and central precocious puberty (CPP) in PWS." (PMID 37685915, 2023). "Loss of function mutations in Makorin Ring Finger Protein 3 (MKRN3), a maternally imprinted gene on chromosome 15, are identified genetic causes of central precocious puberty." (PMID 36093089, 2022). "Although mutations in multiple genes such as kisspeptin system, MKRN3, DLK1 have been identified in sporadic and familial cases of central precocious puberty (CPP), many factors involved in pubertal initiation and transition remain poorly understood." (PMID 33381157, 2020). "In addition, also the region near MKRN3, one of the most important genes in pubertal development, is less methylated in girls with central precocious puberty." (PMID 38909248, 2024). "In particular, loss-of-function mutations in the paternally expressed imprinted genes makorin ring finger 3 (MKRN3) and delta-like 1 homolog (DLK1) have been shown to cause central precocious puberty, suggesting the important role of imprinted genes in regulating puberty timing." (PMID 38909248, 2024). "The presence of mutations in the MKRN3, an imprinted gene located in the critical region of PWS on chromosome 15, was associated with familial precocious puberty and might explain it." (PMID 38966214, 2024). "The genetic treatment for accurate MKRN3 compensation may be a promising strategy for central precocious puberty (CPP) therapy." (PMID 35463379, 2022). "Genetic variations in and near the MKRN3 gene have been linked to instances of familial and non-familial central precocious puberty." (PMID 35463379, 2022). "In a study among school-aged girls in Shanghai, the incidence rate of precocious puberty in 2020 was higher than that in 2016-2019; serum concentrations of MKRN3 (makorin ring finger protein 3, a negative regulator of GnRH) were lower and GnRH concentrations were higher in girls from the 2020 group." (PMID 36699035, 2022).
central precocious puberty (continued). "However, until now only the kisspeptin system KISS1/KISS1R, MKRN3, and DLK1 or Pref-1 identified in sporadic or familial central precocious puberty cases have been confirmed causal variants leading to CPP." (PMID 34748517, 2021). "These included the imprinted gene makorin ring finger protein 3 (MKRN3), paternally inherited mutations that have been identified as causal in pedigrees of central precocious puberty (CPP), and delta like non-canonical Notch ligand 1 (DLK1)." (PMID 31220230, 2019). "Recently, genetic variation in and near the makorin RING finger protein 3 (MKRN3) was reported to be associated with cases of familial central precocious puberty as well as in non-familial central precocious puberty." (PMID 30053798, 2018). "This study supports the impact of MKRN3 SNP rs12441827 on precocious puberty in Korean boys." (PMID 30053798, 2018). "Children with central precocious puberty (CPP) who were admitted to the Pediatric Endocrinology Department of Shanghai Ruijin Hospital from 2014 to 2021 were enrolled, of whom 4 FCPP children with MKRN3 gene mutations, including 3 girls and 1 boy, were selected as research subjects." (PMID 41323096, 2025). "Additionally, we found 29 case reports that described abnormalities in only MAGEL2 (associated with Schaaf–Yang syndrome) and 42 case reports with abnormalities in only MKRN3 (associated with central precocious puberty), which are not included in the table." (PMID 34200226, 2021).
Prader-Willi syndrome (20 papers, 2011 to 2025). "MKRN3 is at the boundary of the region of Prader-Willi syndrome (PWS), which is associated with CPP in about 4% of cases, whereas DLK1 is at the locus of Temple syndrome, a rare disorder characterized by CPP in 80% to 90% of cases." (PMID 39839367, 2025). "On the contrary, the MKRN3 gene, located within the Prader-Willi syndrome (PWS) region (15q11.2), is the first gene in which loss-of-function mutations have been related to CPP." (PMID 36619551, 2022). "Makorin RING finger protein 3 (MKRN3) is an important factor located on chromosome 15 in the imprinting region associated with Prader-Willi syndrome." (PMID 36714607, 2022). "Due to MRKN3’s location on the PWS region of chromosome 15, loss of MKRN3 or damage to this gene should be considered in patients with Prader Willi Syndrome patients who develop symptoms of CPP." (PMID 36531492, 2022). "This intronless gene is located within the Prader Willi Syndrome locus of chromosome 15 and encodes the E3 ubiquitin ligase makorin ring finger protein 3 (MKRN3)." (PMID 36531492, 2022). "Very recently, the makorin RING finger protein 3 (MKRN3) gene, located on chromosome 15 in the Prader-Willi syndrome (PWS)-associated region (15q11-q13), has been found mutated in 5 families with familial precocious puberty." (PMID 26499472, 2015). "Both genes are located at critical regions of imprinting disorders that may be associated with CPP (MKRN3 at chromosome 15q11-q13 of Prader-Willi syndrome and DLK1 at chromosome 14q32.2 of Temple syndrome)." (PMID 37385287, 2023). "MKRN3 is a maternally imprinted gene situated in the 15th chromosome in the region deleted in Prader Willi Syndrome." (PMID 36980008, 2023). "The human MKRN3 gene is composed of a single exon and is located on the 15q11.2-q13 chromosome, in the critical region of Prader Willi syndrome and it is subjected to maternal imprinting." (PMID 36187104, 2022). "Human MKRN3, is located on chromosome 15q11-q13 within the critical region of Prader-Willi syndrome (PWS)." (PMID 36714607, 2022). "MKRN3 is associated with Prader Willy Syndrome, NPAP1 both with Prader Willy Syndrome and Angelman Syndrome while DSCAML1 with Down Syndrome." (PMID 28993790, 2017). "Prader-Willi syndrome (PWS) results from the imprinted locus on chromosome 15q11, in which MKRN3 is included, among other genes." (PMID 38021712, 2023). "MKRN3 gene is located in the Prader-Willi syndrome (PWS)-related region (15q11-q13) on chromosome 15." (PMID 31636607, 2019). "Even more, identification of the MKRN3 gene within the Prader-Willi syndrome critical region as the master regulator of pubertal development led to the need of testing the potential link between the MKRN3 gene expression and/or sequence and individual pubertal development in PWS patients." (PMID 40303632, 2025). "Within this shared run, four genes were detected: IGHM (Immunoglobulin heavy constant Mu), MKRN3 (Makorin finger protein 3), MAGEL2 (MAGE family member L2) and NDN (Necdin), located upstream of the Prader-Willi syndrome (PWS) region." (PMID 34695128, 2021). "MKRN3, MAGEL2 and NDN are three protein-coding genes located in the human 15q11-13 imprinted region, and the absence of the paternal contribution of this chromosomal region could lead to human Prader-Willi syndrome, characterized by neurogenetic disorders." (PMID 34359112, 2021). "Deletion of genes from this region inherited from the father (MKRN3, MAGEL2, NDN, SNURF-SNPRN genes) leads to Prader-Willi syndrome (PWS)." (PMID 33375093, 2020). "Deficiencies of other imprinted genes in the region, including MKRN3, MAGEL2 and/or NDN apparently play a role but not sufficient alone to generate the cardinal features recognized in Prader-Willi syndrome." (PMID 22043168, 2011).
Angelman syndrome (5 papers, 2017 to 2025). A neurogenetic disorder characterized by severe intellectual deficit and distinct facial dysmorphic features. "Moreover, a cluster of genes in the BTA21 (GABRG3, MAGEL2, MKRN3, NDN, SNRPN, and SNURF) was significantly associated (FDR = 1.07 × 10−6) with the Prader-Willi and Angelman syndromes pathway in the PPI analysis." (PMID 35692843, 2022). "MKRN3, MAGEL2 and NDN are three maternally imprinted genes in the human Prader-Willi and Angelman syndromes imprinted locus at 15q11-q13." (PMID 34359112, 2021).
non-small cell lung carcinoma (4 papers, 2022 to 2025). A group of at least three distinct histological types of lung cancer, including non-small cell squamous cell carcinoma, adenocarcinoma, and large cell carcinoma. "MKRN3 is frequently mutated in non–small-cell lung cancers (NSCLCs), and genomic aberrations of MKRN3 are found to be enriched in NSCLC samples harboring KRAS mutations." (PMID 35281811, 2022). "In addition, as an E3 ubiquitin ligase, MKRN3 mutations are associated with the progression of osteosarcoma and non-small cell lung cancer." (PMID 37723588, 2023). "E3 ligase MKRN3 is a tumour suppressor regulating PABPC1 ubiquitination in non‐small cell lung cancer, and PABPC1 signalling controlled the secretion of miR‐19a‐3p by CD8 T cells." (PMID 36822595, 2023). "Other studies have reported that MKRN3 inactivation can promote lung cancer progression, but in this study, no lung cancer was observed in rabbits with MKRN3 gene mutations." (PMID 39854156, 2025).
gastric cancer (3 papers, 2019 to 2021). A primary or metastatic malignant neoplasm involving the stomach. "Thus far, MKRN3 has only been found as an oncogene associated with gastric cancer and imprinted genes in the process of human osteosarcoma." (PMID 34689784, 2021). "For example, LncRNA-PCTA6 participates in the endogenous competition of miR-30 by targeting the Makorin RING finger protein 3 to promote the malignant transformation of gastric cancer." (PMID 34712324, 2021). "Interestingly, very recent evidence has preliminarily documented an interplay between miR-30 and MKRN3 in the context of gastric cancer, while miR-30 has been shown to modulate E3 ubiquitin ligase activity in ovarian cells." (PMID 31697675, 2019).
hypogonadism (3 papers, 2020 to 2023). A disorder characterized by decreased function of the gonads. "MKRN3, NDN, and SNORD116, genes that are located in the PWS critical region, have been associated with GnRH secretion and hypothalamic dysfunction leading to hypogonadism." (PMID 34640379, 2021).
osteosarcoma (3 papers, 2021 to 2023). A usually aggressive malignant bone-forming mesenchymal neoplasm, predominantly affecting adolescents and young adults. "Here, we found MKRN3 expression was lower in the high-risk group, and the lower expression of MKRN3 had a tendency to be associated with a worse overall survival in osteosarcoma." (PMID 35281811, 2022). "Currently, MKRN3 is considered a novel imprinted gene involved in the progression of osteosarcoma and non–small cell lung cancer." (PMID 34689784, 2021). "Therefore, MKRN3 might be a protective factor in osteosarcoma." (PMID 35281811, 2022).
neuroblastoma (2 papers, 2020 to 2022). Neuroblastoma (NB) is the most common solid, extracranial childhood tumor. "One surprising aspect of the RBPs discussed in this paper is that some proteins are found in the serum of patients and thus are putative non-invasive biomarkers of neuroblastoma (e.g., MKRN3, DHX9) and, possibly, differentially secreted into serum." (PMID 32707690, 2020).